CD4 (CD4 molecule)
Diseases named in the same sentence as CD4 in open-access papers (continued):
Sharing a sentence is not in itself a finding about the gene and the disease.
atherosclerosis (continued). "Secondly, B cell deficiency impairs CD4 T cell pathogenicity in atherosclerosis." (PMID 31998318, 2019). "It is still unclear to what extent the risk of atherosclerosis is elevated in patients who commence ART at high CD4 counts, especially as individuals may be treated with ART for many decades, which is longer than follow up studies conducted to date." (PMID 31275317, 2019). "Here, we show that atherosclerosis development is severely hampered in mice with T cell-specific Atg7 deficiency and that this is associated with decreased hepatic steatosis and by decreased frequencies of CD4+, CD8+ T cells, and natural killer T (NKT) cells." (PMID 30619297, 2018). "Atherosclerosis development was severely impaired in mice with T cell-specific Atg7 deficiency which can be explained by low levels of serum cholesterol and low numbers of CD4+ T cells, CD8+ T cells and NKT cells." (PMID 30619297, 2018). "In addition, the expression of CX3CR1 was reported on CMV-specific CD4+ T cells in patients showing HIV-associated atherosclerosis." (PMID 29915583, 2018). "Moreover, the importance of T cells in atherogenesis has been highlighted by animal studies showing that transfer of CD4+ T cells aggravates, whilst CD4+ T cell deficiency attenuates atherosclerosis in apoE-/- mice." (PMID 25253303, 2014). "Besides their role in atherosclerosis, macrophages and CD4+ T cells have been implicated in ischemia‐induced neovascularization through the synthesis of local angiogenic/arteriogenic factors." (PMID 24744903, 2014). "The positive associations found in our study between CD4+ memory cells, which reflect previous activation of adaptive immune responses, and measures of subclinical atherosclerosis are consistent with clinical research, mouse model data, and a limited number of population-based epidemiology studies." (PMID 24009662, 2013). "Further, antigen presentation by APCs to CD4+ T cells in the arterial wall has been reported to cause local T cell activation and production of proinflammatory cytokines that promote atherosclerosis by maintaining chronic inflammation and induction of foam cell formation." (PMID 23560095, 2013). "We hypothesized that activation of adaptive immune responses, as reflected by higher proportions of circulating CD4+ memory cells and lower proportions of naive cells, would be associated with subclinical atherosclerosis." (PMID 24009662, 2013). "Circulating TEM cells are associated with increased atherosclerosis and coronary artery disease in humans and in animal models and could represent a key CD4+T-cell subset related to the atherosclerotic process." (PMID 23130116, 2012). "Since the capability of DCs to prime CD4+ T cells is equivalent in normo- and hypercholesterolemic mice, DCs may initiate the Th1 priming associated with aggravated atherosclerosis as well as the Th2 response present in splenocytes of mice given high fat diet." (PMID 21126329, 2010). "Here, we tested OEA using in vitro naïve CD4+ T-cell polarization assays and in vivo atherosclerosis models." (PMID 42248455, 2026). "CD4 T cells can differentiate into different TH or Treg cell subtypes, which can modulate the response of other immune cells and exert direct pro- or anti-inflammatory effects, making the diverse roles of CD4 T cells in atherosclerosis." (PMID 40950552, 2025). "CD8+ T-cells and also CD4+ T-cells, albeit to a lesser extent, are activated during early stages of vein graft atherosclerosis." (PMID 40737954, 2025). "Our findings revealed a progressive accumulation of memory CD4+ T cells in parallel with a corresponding decrease of naive CD4+ T cells during the early and middle stages of atherosclerosis progression." (PMID 41143276, 2025).
atherosclerosis (continued). "CD4+ T cells significantly influence the progression of atherosclerotic plaques, as demonstrated by crossing apoE−/− mice, which are prone to atherosclerosis, with immunodeficient scid/scid mice." (PMID 39940640, 2025). "A transcriptomic study of human APOB-specific CD4 T cells suggests that the transformation of Tregs into exTregs promotes the development of atherosclerosis in both mice and humans." (PMID 39944697, 2025). "In conclusion, our study suggests that legumain plays a key role in regulating CD4+ T‐cell function and the progression of atherosclerosis." (PMID 39473192, 2025). "Under conditions of chronic unresolved inflammation characteristic of atherosclerosis, regulatory CD4+ T cells (Tregs) become unstable and convert to cytotoxic exTregs." (PMID 41120678, 2025). "Atherosclerosis is significantly impacted by various types of white blood cells, with T cells, particularly those of the CD4+ lineage, playing a substantial role in its development." (PMID 39736852, 2025). "In atherosclerosis, IL-27 has been primarily identified as a pro-atherosclerotic cytokine, by promoting adhesion molecule upregulation in endothelial and CD4+ T cells." (PMID 41302192, 2025). "Conversely, application of a STAT3 inhibitor has been shown to alleviate atherosclerosis by suppressing endothelial dysfunction, macrophage differentiation and CD4+ T effector activation." (PMID 41423554, 2025). "Studies have shown that CGC+ CD4+ T cells are higher in PLWH than PWoH with diabetes and are associated with subclinical atherosclerosis." (PMID 40244289, 2025). "In comparison to the control group, the atherosclerosis group demonstrated reduced levels of naïve B cells, plasma cells, CD4+ memory resting T cells, CD4+ memory activated T cells, monocytes, resting mast cells, and activated dendritic cells." (PMID 41031220, 2025). "In both mice and humans, the ratio of CD8 to CD4 is elevated depending on the level of atherosclerosis." (PMID 39944697, 2025). "In contrast, CTLA - 4 inhibition promotes CD4+ T cell differentiation to T-helper type 1 (Th1) cells, ultimately exacerbating atherosclerosis." (PMID 40959093, 2025). "In a mouse model of atherosclerosis, many CD4+ T cells in lymph nodes and atherosclerotic plaques exhibit a memory T cell phenotype, characterized by the expression of surface markers such as CD44." (PMID 39473192, 2025). "At the higher stage of atherosclerosis, the proportion of PD - 1+ Tim-3+ CD4+ T cells was higher in peripheral or arterial blood of patients." (PMID 40959093, 2025). "It is currently believed that ICI treatment activates T cells that recognize atherosclerosis-specific autoantigens, leading to the clonal expansion of autoreactive CD4+, CD8+, and other T cell subsets." (PMID 40821806, 2025). "In conclusion, the present study demonstrated that legumain affects the progression of atherosclerosis by modulating CD4+ T cell biology, which is a novel immunological molecular mechanism of legumain in the pathogenesis of atherosclerosis." (PMID 39473192, 2025). "Clinically, the substantial increases in CX3CR1+/CD4+ T‐cells observed here are of particular note since inhibition of CX3CR1 to ameliorate atherosclerosis progression is promising, as is CX3CR1 modulation in the treatment of CKD." (PMID 38979792, 2024). "Naïve CD4+ T cells can differentiate into subtypes (including Th1, Th2, Th17, Treg), each with distinct effects on atherosclerosis." (PMID 39000373, 2024). "Cell division cycle 42 (CDC42) regulates CD4+T-cell differentiation and participates in vascular stiffness and atherosclerosis and is involved in the progression of Stanford type B aortic dissection (TBAD)." (PMID 38476381, 2024).
atherosclerosis (continued). "Here, we discuss the most prevalent subtypes of CD4+ T cells and their pivotal role during the progression of atherosclerosis." (PMID 38774746, 2024). "While CD4+ T cell functions have been extensively studied in atherosclerosis, the role of CD8+ cytotoxic T cells in this context is less well known." (PMID 39161593, 2024). "Krüppel-like factor 10 (KLF10) is a transcription factor in CD4+ T cells, which can regulate the progression of atherosclerosis." (PMID 39582868, 2024). "FOXP3 is a master transcription factor in Treg cells, a CD4+ T cell subset crucial to dampening inflammatory responses, and they have been reported to play a protective role in atherosclerosis." (PMID 38892400, 2024). "The identified APOB-reactive expanded CD4+T cell clones and conserved motifs can be used to annotate and track human atherosclerosis-related autoreactive CD4+T cells and measure their clonal expansion." (PMID 38571941, 2024). "Some studies support the concept of atherosclerosis as a true autoimmune T-cell disease affecting the arterial wall where the autoimmune component of atherosclerosis is driven by autoreactive CD4+ T cells." (PMID 38892201, 2024). "This indicates that the role of CD4+ T cells in atherosclerosis is much greater than previously recognized." (PMID 38558932, 2024). "Specifically, naive CD4+ T cell subgroups are correlated with atherosclerosis and coronary artery disease." (PMID 39610972, 2024). "Our results reveal that Aza converts naive CD4+ T cells into functional Tregs by inhibiting Dnmt1, and the transfer of Aza-iTregs suppresses atherosclerosis in mice." (PMID 39304654, 2024). "We generated induced Tregs (iTregs) from CD4+ T cells by using Aza in vitro, and this was followed by the intravenous infusion of iTregs for the treatment of atherosclerosis." (PMID 39304654, 2024). "Neutralizing IL-17A blocked atherosclerosis progression in Apoe -/- mice on a high-fat diet, and inhibiting CD4+ T cell polarization slowed coronary disease progression." (PMID 39723414, 2024). "PD polarized CD4+ T‐cells toward an inflammatory Th1/Th17 phenotype, and increased CX3CR1+ CD4+ T‐cells, which are associated with vascular homing in CKD‐associated atherosclerosis." (PMID 38979792, 2024). "Subcutaneous infusion of apolipoprotein B100 (ApoB100) to ApoE−/− mice was associated with abrogated atherosclerosis development and progression of atherosclerosis, which also appeared to be CD4+CD25+ Treg-dependent." (PMID 39061983, 2024). "PD exposure in uremic mice undoubtedly triggers local peritoneal inflammation, but here we show a strong CD4+ T‐cell and macrophage phenotype distant to the peritoneal cavity, leading to aggravated atherosclerosis." (PMID 38979792, 2024). "In contrast, adoptively transferred PI3Kδ–/– CD4+CD25+ Tregs were unable to attenuate atherosclerosis, strongly suggesting that PI3Kδ deficiency specifically in Tregs aggravates atherosclerotic lesion formation." (PMID 39378110, 2024). "The results suggest a correlation between naive CD4+ T cells and atherosclerosis, further supporting the potential role of naive CD4+ T cells in atherosclerosis." (PMID 39610972, 2024). "Given that atherosclerosis, vascular stiffness, and abnormal differentiation of CD4+T cells are involved in TBAD progression, CDC42 is suspected to serve as a biomarker for TBAD patients in clinical practice." (PMID 38476381, 2024). "In our early atherosclerosis model, we reveal that immunoproteasomal inhibition can reduce CD4+ and CD8+ Tem and Tcm cell populations in several immune compartments." (PMID 38660806, 2024). "Early arterial walls predominantly host regulatory T (Treg) cells, but this shifts to CD4+ effector T cells (T helper cells) during atherosclerosis onset, with Treg reduction impairing immune tolerance to self-antigens and facilitating disease progression." (PMID 39766344, 2024).
atherosclerosis (continued). "Inversion of the CD4/CD8 ratio has been identified as a hallmark of immune senescence and a predictor of early atherosclerosis." (PMID 37705002, 2023). "Overall, these results confirmed that CD4+ T cells in NC exhibited anti-inflammatory function, while in atherosclerosis, the anti-inflammatory function was drastically reduced." (PMID 37706320, 2023). "In conclusion, our data suggest that atherosclerosis has an autoimmune compondent driven by autoreactive CD4+ T cells." (PMID 38665903, 2023). "Valsartan can reduce the systolic pressure of Ang II treated ApoE-/- mice, promote the differentiation of CD4+T cells into Th2 cells and Tregs, improve the immune balance, and stabilize the atherosclerosis plaque." (PMID 36911741, 2023). "CD4+ T helper 2 cells express IL-4 and IL-13, but their impact on atherosclerosis is controversial mainly due to the dubious function of IL-4." (PMID 38138958, 2023). "A number of studies have shown that CD4+ Treg cells are crucial in the maintenance of peripheral tolerance and have an important role in the control of atherosclerosis-related inflammation." (PMID 37763334, 2023). "Atherosclerosis-specific C3 CD4+ T cells had slightly increased GZMA expression compared to PSA PBMCs and SF." (PMID 38665903, 2023). "CD4+ T cells from which T helper cells are differentiated have important roles in atherosclerosis development." (PMID 37600028, 2023). "The single cell RNA sequencing data indicated that DPP4 was mainly expressed in cl.3 (CD4+ T cells) and was highly upregulated in CD4+ T cells in atherosclerosis." (PMID 36683148, 2023). "Here we highlight the most recent advances in our understanding of the roles of FOXP3-expressing CD4+ Treg cells in the atherogenic process and discuss potential translational strategies for the treatment of atherosclerosis by Treg manipulation." (PMID 37763334, 2023). "Abatacept, a syngeneic analog of CTLA‐4, prevented CD4+ T‐cell activation and reduced atherosclerosis progression by 78% in the femoral artery of mice." (PMID 37584246, 2023). "In this review, we describe the role of CD4+ Treg cells in the natural course of atherosclerosis and discuss potential opportunities for the development of Treg-focused approaches for anti-atherogenic therapy." (PMID 37763334, 2023). "Recent single TCR sequencing studies suggest that atherosclerosis has an auto-immune component driven by autoreactive CD4+ T-cells [50••]." (PMID 37395922, 2023). "For some time now, regulating CD4+ T cells (Tregs) have been shown to protect mice from atherosclerosis in animal models." (PMID 37373933, 2023). "From these results and in vivo data, they concluded that Nrp-1 aids in the migration of CD4+ effector T cells into the aortic tissue and draining lymph nodes and worsen the outcome of atherosclerosis." (PMID 38019895, 2023). "Including active smoking, age and a CD4/CD8 ratio < 0.7 in a prediction equation for subclinical atherosclerosis by means of logistic regression achieved good predictive power." (PMID 36627565, 2023). "Tobacco use, age and a CD4/CD8 ratio below 0.7 allow prediction of the presence of subclinical atherosclerosis in primary prevention." (PMID 36627565, 2023). "Subsequently, CD4+ and CD8+ T cells of both diseases were integrated and projected on the atherosclerosis CD4+ and CD8+ UMAP as reference." (PMID 38665903, 2023). "Overexpression of CTLA-4 prevented the development of atherosclerosis by suppressing the activation of effector CD4+ T cells and restricting their accumulation along the arterial wall in hyperlipidemic mice." (PMID 37297017, 2023). "Adoptive transfer experiments in Rag1−/− mice using Dpp4+/+ and Dpp4−/− T cells demonstrated reduced atherosclerosis and attenuated CD4+ and CD8+ T‐cell infiltration in mice with Dpp4−/− T cells." (PMID 36683148, 2023). "B2 cells can promote atherosclerosis by producing IgG, secreting pro-inflammatory cytokines, and activating CD4 T cells." (PMID 38221996, 2023).
atherosclerosis (continued). "Another study reported that CD4+ T cells were major proatherogenic cells in a mice model of atherosclerosis." (PMID 36988256, 2023). "Consistent with single cell RNA sequencing results, DPP4+ (including both DPP4low and DPP4high) cells in CD4+ T‐cell population was significantly increased in patients with atherosclerosis." (PMID 36683148, 2023). "The analyses showed plaque-specific clonal expansion in effector CD4+ T cells, expressing genes indicative of exposure to activating antigens, thus suggesting that atherosclerosis has an autoimmune component driven by autoreactive CD4+ T cells." (PMID 38665903, 2023). "In time, with the progression of atherosclerosis, the number of circulating Treg lessens, and the total CD4+ T cells increase, suggesting a pro-active phenotypic transformation of Treg cells." (PMID 37600028, 2023). "We found that Dpp4 was mainly expressed in cl.3 (CD4+ T lymphocytes) and was further increased in CD4+ T lymphocytes from patients with atherosclerosis." (PMID 36683148, 2023). "The CD4+ T cells of the NC were clearly shifted toward more differentiated states compared with those of the atherosclerosis: most of the T cells in the NC were placed in the latest pseudotime corresponding to anti-inflammatory T cells." (PMID 37706320, 2023). "In fact, CD4+ T-cell subsets and their effector cytokines have distinct excitatory or inhibitory effects on both tumors and atherosclerosis." (PMID 37297017, 2023). "This is the first time that a distinctive, validated miRNA profile from circulating CD4+ T cells in atherosclerosis has been presented." (PMID 35428200, 2022). "Considering the importance of adaptive immunity in atherosclerosis, we performed another miRNA array with CD4+ T cells collected from patients with ASO." (PMID 35428200, 2022). "Involvement of CD4+ T cells has been recognized in the pathogenesis of several cardiovascular diseases including atherosclerosis, myocardial infarction, and myocarditis." (PMID 36211827, 2022). "By comparison, CD4+ T cells in atherosclerosis are better characterized, but display a more complex relationship with the disease due to the different possible subtypes of the CD4+ T cell." (PMID 36461105, 2022). "Ox-LDL is widely considered as the main antigen involved in the inflammation of LEASO, and ox-LDL-specific CD4+T cells have been suggested to play a crucial role in atherosclerosis." (PMID 35757718, 2022). "Elucidation of the complex gene regulatory network that controls CD4+ T cell immune events will substantially enhance our understanding of the development of atherosclerosis and subsequent cardiovascular diseases." (PMID 35428200, 2022). "Previous studies documented that the CD4+ T cell was tightly connected with vascular conditions, including atherosclerosis, hypertension, and AD." (PMID 36105536, 2022). "In atherosclerosis-susceptible mice, CD40L deficiency in CD4+ T cells shows impaired Th1 polarization, mainly reflected in the reduced production of pro-inflammatory IFN-γ, thus alleviating the development of atherosclerosis." (PMID 36685487, 2022). "In the Multi-Ethnic Study of Atherosclerosis (MESA), naïve and memory CD4 + T cells were cross-sectionally associated with type II diabetes and subclinical atherosclerosis." (PMID 35858901, 2022). "An analysis of leukocyte populations indicates that telomere shortening is a predictor of atherosclerosis and cardiovascular disease; moreover, both CD4+ and CD8+ TEMRA cells are considered to predict cardiovascular-related mortality in older individuals." (PMID 36082127, 2022). "These CD4+ T cell subpopulations can secrete a variety of cytokines to promote or suppress the development of inflammation, thereby regulating atherosclerosis progression." (PMID 36211578, 2022).